LAMC1 (laminin subunit gamma 1)
Diseases named in the same sentence as LAMC1 in open-access papers (continued):
Sharing a sentence is not in itself a finding about the gene and the disease.
prostate carcinoma (7 papers, 2015 to 2025). A carcinoma that arises from epithelial cells of the prostate gland. "Similarly, higher expression of LAMC1 is associated with a shorter tumor recurrence time and decreased patient survival in meningiomas, cancer cell migration, invasion in human prostate cancer cells, and tumor progression of the endometrioid carcinoma." (PMID 31884422, 2019). "LAMC1 overexpression also indicated poor prognosis for cutaneous squamous cell carcinoma and prostate cancer." (PMID 34512203, 2021). "Consistent with our findings in melanoma, LAMC1 suppression by miR-29a/b/c has been shown to influence prostate cancer cell migration and invasion." (PMID 27852308, 2016). "Silencing of LAMC1 significantly inhibited cell migration and invasion in prostate cancer cells." (PMID 34771544, 2021).
glioma (6 papers, 2021 to 2025). A benign or malignant brain and spinal cord tumor that arises from glial cells (astrocytes, oligodendrocytes, ependymal cells). "Kaplan–Meier survival analysis showed that high LAMC1 expression was associated with a poor prognosis of patients with glioma." (PMID 38678297, 2024). "Data from the Chinese Glioma Genome Atlas also showed high expression of LAMC1 in glioma associated with poor prognoses." (PMID 38678297, 2024). "Concomitantly, high LAMC1 expression is associated with poor prognosis in gliomas and in GBM according to data from the Gravendeel, Rembrandt and TCGA data sets." (PMID 34158478, 2021). "This study demonstrates the biological function, clinicopathological correlation, and clinical prognostic value of LAMC1 gene expression in pan-cancers, and conducted experimental verification based on glioma." (PMID 38678297, 2024). "An early study of LAMC1 expression in glioma indicated its prognostic value using the log-rank test and Cox analysis." (PMID 38678297, 2024). "This study conducted pan-cancer bioinformatics analysis of the LAMC1 gene and explored its biological characteristics and mechanism-of-action in glioma." (PMID 38678297, 2024). "The hypoxic microenvironment in gliomas activates the HIF-1α/LAMC1 signaling, thereby promoting tumor progression." (PMID 38678297, 2024). "We also found that HIF-1α had a positive correlation to LAMC1 expression in glioma, which led to analyzing the mechanism of HIF-1α-mediated LAMC1 expression." (PMID 38678297, 2024). "In clinical glioma tissues, LAMC1 protein was highly expressed and correlated to poor overall survival." (PMID 38678297, 2024). "Our investigation revealed that high LAMC1 expression in some TCGA cancers including glioma indicated a poor prognosis." (PMID 38678297, 2024). "Using a glioma tissue microarray, LAMC1 protein was again found to be highly expressed and positively associated with the pathological grade of glioma." (PMID 38678297, 2024). "The results from TCGA and CGGA databases showed that LAMC1 expression in gliomas was significantly higher than that in normal brain tissue, and high expression of LAMC1 was an independent indicator of prognosis." (PMID 38678297, 2024). "Fluorescence microscopy showed that lentiviral particles had a higher infection efficiency in glioma cells, and western blotting verified the efficacy in LAMC1 knockdown or overexpression." (PMID 38678297, 2024). "LAMC1 expression in most cancers in The Cancer Genome Atlas (TCGA) including glioma was significantly higher than that in normal tissues, which had a poor prognosis and were related to various clinicopathological features." (PMID 38678297, 2024). "Correlation analysis showed that HIF-1α expression in normal brain tissue and glioma was positively correlated to LAMC1 (r = 0.499, P < 0.001)." (PMID 38678297, 2024). "Targeted intervention on the HIF-1α/LAMC1 signaling attenuates cell growth and invasion, suggesting a new strategy for glioma treatment." (PMID 38678297, 2024). "Glioma patients with higher pathological grades (G2–4) had higher total immunoreactive scores for LAMC1 than those with a lower grade (G1) (P < 0.05)." (PMID 38678297, 2024). "To further reveal the function of the change in LAMC1 expression during the development and pathological progression of glioma, we used lentiviral vectors to establish cell models with reduced or enhanced LAMC1 expression." (PMID 38678297, 2024). "We conducted comprehensive bioinformatics analysis of LAMC1 gene expression and clinical relevance in pan-cancer datasets of public databases and validated LAMC1 expression in glioma tissues and cell lines." (PMID 38678297, 2024). "LAMC1 knockdown in Hs683 glioma cells attenuated cell proliferation, migration, and invasion, while overexpression of LAMC1 in U251 cells leads to the opposite trend." (PMID 38678297, 2024).
glioma (continued). "In gliomas, LAMC1 expression increases with grade, where LAMC1 is more expressed in GBM (grade IV) than lower grade gliomas." (PMID 34158478, 2021). "In agreement with the NCI-60 cell line screening, a positive correlation between LAMC1 mRNA levels and H-1PV oncolysis was also found in glioma cell lines." (PMID 34158478, 2021). "However, the in vitro results suggest that LAMC1 plays a crucial role in the biological processes of glioma cells." (PMID 38678297, 2024). "More importantly, we confirmed the existence of a HIF-1α/LAMC1 axis in the glioma hypoxic microenvironment, which may be a major mechanism regulating its malignant phenotype." (PMID 38678297, 2024). "Bioinformatics analysis of LAMC1 expression in gliomas was performed using the CGGA database." (PMID 38678297, 2024). "High expression of LAMC1 in some solid tumors including gliomas suggests a poor prognosis." (PMID 38678297, 2024). "We further explored the mechanisms mediating LAMC1 expression in gliomas." (PMID 38678297, 2024). "In the current study, we explored the mechanistic role of LAMC1 in glioma." (PMID 38678297, 2024). "Therefore, the increase in LAMC1 expression in glioma was at least partly mediated directly through HIF-1α." (PMID 38678297, 2024). "Therefore, on the basis of the bioinformatics analysis of multiple public databases combined with the clinical data validation, LAMC1 may be a prognostic biomarker of gliomas." (PMID 38678297, 2024). "Hence, targeted treatment of the HIF-1/LAMC1 signaling axis may be a novel therapeutic strategy for gliomas." (PMID 38678297, 2024). "Therefore, therapeutic strategies based on inhibition of the HIF-1α/LAMC1 axis to disrupt the tumor hypoxic microenvironment may be a promising approach for glioma treatment." (PMID 38678297, 2024). "In this study, high expression levels of LAMC1 were found in IDH-wildtype and 1p19q non-coding glioma compared with IDH-mutants or 1p19q codeletions." (PMID 38678297, 2024). "Clinicopathological characteristic correlation analysis of the CGGA data demonstrated that the expression level of LAMC1 was remarkably related to age, grade, PRS type, chemotherapy, and histology in glioma samples." (PMID 38678297, 2024). "We recently described four glioma cell lines that are semi-permissive to H-1PV infection, namely U251, LN308, T98G and A172-MG, which all express low levels of LAMC1 mRNA." (PMID 35632759, 2022). "Interestingly, most of these proteins are ECM molecules and contribute to the invasiveness of glioma cells, including FN1, TNC, LAMC1, COL1A1, EGFR, CDK6, and COL6A2." (PMID 37059730, 2023). "Notably, while confirming that the HIF-1α inhibitor YC-1 has no significant cytotoxicity on glioma cells, we have noticed that YC-1 downregulates the expression of LAMC1 while inhibiting HIF-1α expression at the same time." (PMID 38678297, 2024).
colon cancer (5 papers, 2019 to 2025). "Our PheWAS results also indicate the index variants at LAMC1 and LAMA5 are significantly associated with colon cancer." (PMID 38582945, 2024). "In support of the increased cancer-specific production of these laminin chains, we identified significantly greater expression of LAMA5, LAMB1 and LAMC1 transcripts in colon cancer tissues compared with normal colon in publicly available gene array data using the OncomineTM platform." (PMID 31064120, 2019). "Among others, human LAMA5, LAMB1 and LAMC1 transcripts were expressed at high levels, with little or no expression of human collagen IV identified, indicating that the laminins required for vascular basement membrane assembly are produced by metastatic colon cancer cells." (PMID 31064120, 2019). "We identified seven EMT-related genes (TPM1, LAMC1, POSTN, CCN1, MGP, PCOLCE2, and DPYSL3) with prognostic significance in patients with colon cancer from TCGA and GSE17536 cohorts." (PMID 34180352, 2021).
esophageal squamous cell carcinoma (5 papers, 2021 to 2025). Esophageal squamous cell carcinoma (ESCC) is a type of esophageal carcinoma (EC) that can affect any part of the esophagus, but is usually located in the upper or middle third. "LAMC1 secretion was associated with the formation of inflammatory CAFs in esophageal squamous cell carcinoma, and upregulation of LAMC1 expression promoted CXCL1 secretion, which stimulated inflammatory CAFs via CXCR2-pSTAT3 and thus promoted tumor progression." (PMID 37588985, 2023). "LAMC1 promoted CXCL1 secretion, which stimulated inflammatory CAF formation via CXCR2-pSTAT3, which in turn accelerates esophageal squamous cell carcinoma progression." (PMID 36246404, 2022). "Notably, in esophageal squamous cell carcinoma (ESCC), TGF-β1-induced LAMC1 expression promotes CXCL1 secretion, which in turn activates the AKT-NFκB signaling axis, leading to the formation of inflammatory CAFs (iCAFs)." (PMID 40490643, 2025).
glioblastoma (5 papers, 2009 to 2022). The most malignant astrocytic tumor (WHO grade IV). "In glioblastoma, we identified an RND1low signature of six genes (ITGA5, COL3A1, COL5A1, MET, COL1A2, LAMC1), upregulated in glioblastoma patients with low RND1, that predicts the overall survival of glioblastoma patients." (PMID 31344837, 2019). "After miR‐218 overexpression in glioblastoma cells, we observed a decrease in the expression levels of GBM oncogenes such as PIK3CA, ROCK1, LAMC1 and ICAM1." (PMID 35702951, 2022). "Finally, based on signaling pathways activated in patients with low levels of RND1, we identified an RND1low signature of six genes (MET, LAMC1, ITGA5, COL5A1, COL3A1, COL1A2) that is an independent prognostic factor in glioblastoma." (PMID 30333910, 2018).
melanoma (5 papers, 2016 to 2025). A malignant, usually aggressive tumor composed of atypical, neoplastic melanocytes. "Our findings implicate miR-29b as a regulator of cellular phenotype in melanoma through proteins including LAMC1 and PPIC within a network of post-transcriptionally regulated genes." (PMID 27852308, 2016). "Furthermore, treatment with the specific LAMC1 peptide enhanced pulmonary metastasis of B16 melanoma cells and induced the production of matrix metalloproteinase-9 from B16 cells." (PMID 34268116, 2021). "Moreover, treatment with LAMC1 peptide C-16 increases the pulmonary metastases of B16-F10 mouse melanoma cells." (PMID 31884422, 2019). "We also evaluated the expression of ECM proteins, including laminin (LAMC1) and fibronectin, both of which were abundantly expressed in the MEWO melanoma cells." (PMID 40869090, 2025). "We examined LAMC1 and PPIC in detail as potential mediators of miR-29b-3p effects across our melanoma cell models." (PMID 27852308, 2016).
ovarian carcinoma (4 papers, 2021 to 2023). A malignant neoplasm originating from the surface ovarian epithelium. "Overexpression of LAMA4, LAMB1, and LAMC1 mRNAs has been associated with lower overall survival (OS) and progression-free survival (PFS) in ovarian cancer." (PMID 38031074, 2023). "The results show that ETS1 transcriptionally regulates the expression of LAMA5, LAMB1, and LAMC1 in ovarian cancer cells." (PMID 36477408, 2022). "The laminin family members LAMA5, LAMB1, and LAMC1 were the most prominently upregulated proteins in LV-ETS1 Exos of the two ovarian cancer cell lines." (PMID 36477408, 2022). "According to qRT-PCR and western blotting data, ETS1 regulated the expression of LAMA5, LAMB1, and LAMC1 in ovarian cancer cells." (PMID 36477408, 2022). "Nevertheless, the pathways affected by LAMC1 in ovarian cancer remain to be determined." (PMID 34512203, 2021). "In ovarian cancer samples from the TCGA database, the expression levels of LAMA5, LAMB1, and LAMC1 were positively correlated with that of ETS1." (PMID 36477408, 2022). "In a survival analysis of patients with ovarian cancer in the GSE9891 dataset, increased expression of LAMA5, LAMB1, and LAMC1 was related to shorter overall survival." (PMID 36477408, 2022). "ETS1 overexpression altered the size of exosomes derived from ovarian cancer cells, and upregulated the expression of three laminins, LAMA5, LAMB1, and LAMC1, in ovarian cancer cells and their exosomes." (PMID 36477408, 2022).
meningioma (3 papers, 2019 to 2022). A generally slow growing tumor attached to the dura mater. "The proteins decorin, integrin alpha-M, fibronectin, microfibrillar-associated protein 5, laminin subunit gamma-1, among others, participate in the organization of ECM and were identified exclusively or upregulated in male meningioma." (PMID 32587372, 2020).
Obesity (3 papers, 2022 to 2025). Accumulation of substantial excess body fat. "Similar to LAMA4 and LAMB1, LAMC1 is closely related to adipogenic differentiation, with significant overexpression in obesity-associated samples." (PMID 40130165, 2025).
cholangiocarcinoma (2 papers, 2022). A carcinoma that arises from the intrahepatic biliary tree (intrahepatic cholangiocarcinoma) or from the junction, or adjacent to the junction, of the right and left hepatic ducts (hilar cholangiocarcinoma). "After that, we verified that LAMC1 was enhanced in cholangiocarcinoma and boosted cellular malignant progress." (PMID 35022330, 2022). "In terms of mechanisms, we confirmed that PSMA3-AS1 upregulated LAMC1 by sponging of miR-376a-3p, thereby expediting cholangiocarcinoma deterioration." (PMID 35022330, 2022). "PSMA3-AS1 can upregulate laminin subunit gamma 1 (LAMC1) to promote the proliferation and migration of cholangiocarcinoma." (PMID 36300088, 2022). "Accordingly, PAX5-induced PSMA3-AS1 boosted occurrence and development of cholangiocarcinoma via mediating miR-376a-3p/LAMC1." (PMID 35022330, 2022). "Besides, we detected influence of LAMC1 on malignant biological behaviors of cholangiocarcinoma, and corroborated that downregulated LAMC1 repressed cellular growth and metastasis, whereas upregulated LAMC1 facilitated these malignant biological behaviors." (PMID 35022330, 2022). "TCGA displayed that LAMC1 was upregulated in cholangiocarcinoma." (PMID 35022330, 2022). "The present research uncovers that PAX5/PSMA3-AS1/miR-376a-3p/LAMC1 expedites cholangiocarcinoma deterioration, and PSMA3-AS1 is hopeful to become an intervention target for cholangiocarcinoma." (PMID 35022330, 2022).
chronic kidney disease (2 papers, 2021 to 2022). Impairment of the renal function secondary to chronic kidney damage persisting for three or more months. "Besides, increased LAMC1 protein was also detected in glomerular basement membrane of kidney samples from chronic kidney disease (CKD) patients." (PMID 36188228, 2022). "Immunohistochemical analysis of kidney specimens from patients with Chronic Kidney Disease (CKD) indicated an increased presence of LAMC1 in the glomerular basement membrane that could reflect an acceleration of its remodelling." (PMID 34943605, 2021).
COVID-19 (2 papers, 2022 to 2023). A disease caused by infection with severe acute respiratory syndrome coronavirus 2. "The most changed components of BM included laminins (LAMB2, LAMA2, LAMC3, LAMB1, LAMC1, and LAMA5) and proteoglycans (COL18A1, HSPG2, and AGRN), with some BM specific collagens (IV, VIII, XVIII, and V collagens) remaining in COVID-19 brains, as compared with the control brains." (PMID 36609561, 2023). "DNMT3B, LAMC1, MET, NASP, PTEN, and SPARC are upregulated in COVID-19." (PMID 36204652, 2022). "However, the roles of LAMC1, MET, NASP, and SPARC in COVID-19 have not yet been elucidated." (PMID 36204652, 2022).
diabetes (2 papers, 2011 to 2023). "Interestingly, diabetes-related alterations of the extracellular matrix and adhesion molecules were varied; Pecam, Mmp10, Lamc1, Itgb7, Mmp9, and Timp4 were up-regulated, but Col11a1, Fn1, Admts2, and Itgav were down-regulated." (PMID 21984919, 2011).
diabetic kidney disease (2 papers, 2017 to 2024). Progressive kidney disorder caused by vascular damage to the glomerular capillaries, in patients with diabetes mellitus. "Similarly, recent research pointed out that overexpression LAMC1 took part in the immune response and immune infiltration in diabetic kidney disease according to the immunohistochemistry results, which indicates the unique role of LAMC1 in the immune therapy in the future." (PMID 38549047, 2024). "Moreover, LAMC1 is also a candidate gene for diabetic nephropathy." (PMID 29273013, 2017).
endometriosis (2 papers, 2013 to 2021). The growth of functional endometrial tissue in anatomic sites outside the uterine body. "Recently, altered expression of the LAMC1 gene was described in the endometrium of patients with endometriosis (compared with healthy endometrium)." (PMID 24070183, 2013).
endothelial dysfunction (2 papers, 2024 to 2025). In vascular diseases, endothelial dysfunction is a systemic pathological state of the endothelium (the inner lining of blood vessels) and can be broadly defined as an imbalance between vasodilating and vasoconstricting substances produced by (or acting on) the endothelium. "LAMC1, RBMS2, TMOD3, and LRP10 were suggested as key drivers of AD progression associated with endothelial dysfunction." (PMID 41409615, 2025). "Single-cell validation confirmed vascular-endothelial dysfunction, with LAMC1, RBMS2 and TMOD3 upregulated in endothelial cells from female APOE ε4 Alzheimer’s disease brains." (PMID 41409615, 2025).
liver fibrosis (2 papers, 2012 to 2025). "Notably, COL4A2 and LAMC1 were closely associated with ECM-receptor interactions, suggesting that Lira mitigates liver fibrosis by inhibiting these pathways." (PMID 41377138, 2025). "Notably, Lira significantly regulated ECM-receptor interactions, particularly by decreasing LAMC1 and COL4A2 protein levels, suggesting a potential mechanism for ameliorating hepatic fibrosis." (PMID 41377138, 2025).
osteoporosis (2 papers, 2025). A condition of reduced bone mass, with decreased cortical thickness and a decrease in the number and size of the trabeculae of cancellous bone (but normal chemical composition), resulting in increased fracture incidence. "Identifying 8 key genes as potential regulatory target genes for the differentiation of mesenchymal stem cells into osteoblasts or adipocytes under the condition of disuse osteoporosis (ITGB3, LAMC1, COL6A3, ITGA8, PDGFRB, ITGA4, LAMB1, LAMA4)." (PMID 40130165, 2025). "This dysregulation may exacerbate the pathological progression of disuse osteoporosis (DOP), highlighting the critical role of the LINC01123/hsa-let-7i-5p/LAMC1 axis in maintaining bone homeostasis under mechanical unloading conditions." (PMID 40248073, 2025).
pancreatic carcinoma (2 papers, 2021 to 2023). "Pancreatic cancer also has the tendency to metastasize to the peritoneum or omentum, and Laminin gamma 1 (LAMC1) on pancreatic cancer cells promotes their homing to the peritoneum." (PMID 37350937, 2023). "For example, LAMC1 upregulation was found in pancreatic carcinoma and GBM, the two tumour entities in which H-1PV has been tested in the clinic to date." (PMID 34158478, 2021).